EPCAM (epithelial cell adhesion molecule)
Diseases named in the same sentence as EPCAM in open-access papers (continued):
Sharing a sentence is not in itself a finding about the gene and the disease.
cancer (continued). "In double-staining IHC, ALDH1A1 was not co-expressed with BMI1, EpCAM, CD13, CD24, CD90 and CD133, which reported as cancer stem cell markers in HCC." (PMID 26160842, 2015). "In addition, because EpCAM-related intracellular signaling pathways in cancer cells can be activated following binding of anti-EpCAM to neoplastic cells, it is not surprising that subsequent analysis of CTCs perturbed by anti-EpCAM may result in post-isolation artifacts." (PMID 25909226, 2015). "While EpCAM and TROP2 show weak and non-complete membranous staining in normal bronchial epithelium and pneumocyte, their complete membranous expression in carcinoma suggests their role in carcinogenesis." (PMID 22482828, 2012). "We did, however, not observe increased transcript expression of the cancer stem cell markers CD44, CD133 and the epithelial cell adhesion molecule EpCAM." (PMID 19529782, 2009). "In support of this hypothesis, both EpCAM+ CTCs and Clusters > 2 increased after the first metastasis in HER2+ but not HR+ cancers, suggesting discrete evolutionary trajectories in CTC clustering between the receptor statuses." (PMID 40867346, 2025). "To investigate whether EpCAM and HGFR activation cooperatively regulates cancer progression and metastasis, we examined the phosphorylated ERK and AKT levels in EpCAM knockout cells with or without HGF treatment." (PMID 37543570, 2023). "FR@Z-pTA NPs not only capture more than 88% of rare cancer cells for both EpCAM-positive cells (MCF-7, HepG2) and EpCAM-negative cells (MDA-MB-231, HeLa) but also effectively release the captured cells with high efficiency (>80%) and viabilities (>90%) under cell-friendly pH/ATP stimuli." (PMID 40212446, 2022). "These platforms have consistently proven their effectiveness at isolating a greater number of CTCs in samples from patients with different types of cancer, even capturing CTC subtypes that no longer express EpCAM antigens, when compared with approaches based on capture antibodies." (PMID 32372001, 2020). "Therefore, in order to determine the effect of staging on cancer recurrence, the different levels of soluble CD44, CD44v6, CD44v8-10 and EpCAM in patients with and without recurrence were examined according to staging." (PMID 32039729, 2020). "HCT116, MCF7: EpCAM-positive cancer cell lines; HeLa, THP1: EpCAM-negative cancer cell lines." (PMID 30782169, 2019). "The LuCSC-holoclones were EpCAM+ (morphologically epithelial), and negative for classical EMT genes AXL, CD10, Zeb1 and MMP1 that are involved in motility and invasive behavior of mesenchymal cancer cells." (PMID 31069016, 2019). "Especially for malignant tumors, the majority of CTC population has undergone epithelial-mesenchymal transition (EMT) which lacks EpCAM expression and could lead to false negative results in EpCAM-dependent analysis." (PMID 28467771, 2017). "Notably, EpCAM is non-specifically expressed on normal epithelial cells in the circulation, for example in patients with benign colon disease, and it may exhibit reduced expression or even be absent in cancer cells that have undergo an epithelial-to-mesenchymal transition." (PMID 27517159, 2016). "Interestingly, ALDH1A1 was not co-expressed with EpCAM, BMI1, CD13, CD24, CD90 and CD133 which have been reported to be cancer stem cell markers in HCC." (PMID 26160842, 2015). "Using sorted cells and bulk cells or their respective isolated RNA showed that the EpCAM based IE/FACS sorting and capture does not seem to affect the transcriptome of cancer cells at a significant level, as high correlation in gene expression between both populations was found." (PMID 26556851, 2015).
cancer (continued). "We noticed that normal epithelial tissues from the same cancer patient with overexpressed EpCAM were negative for SYL3C staining and that cancer tissue showed strong positive staining of SYL3C, while the random sequence was negative for EpCAM expression." (PMID 26687301, 2015). "KRT19, CEACAM5, EPCAM, DSG3, SFTPA, SFTPC and SFTPB mRNA levels were initially validated by real-time reverse transcription PCR-based quantification in 16 NSCLC tumors and 22 LNs and 12 PB samples from individuals without known cancer." (PMID 23671585, 2013). "Therefore, cell findings of EpCam+ and CD44+ CRC did not overlap which may not exclude the likelihood of the presence of cancer stem phenotype at a very small fraction, yet suggesting that the CD44+ CRC identified in the donors are different to CTC and CEB." (PMID 36100762, 2023). "Importantly, we detected an increased membranous expression and colocalization of β-CAT, E-CAD and EpCAM in the KLF4-overexpressing EpCAM−/CD133− non-stem cells, suggesting that this complex might be required for the cancer stem cell phenotype." (PMID 32408542, 2020). "EpCAM expression was higher in estrogen receptor-negative (ER-) cases (84.6% in ER- cancers versus 74.5% in ER+ cancers, P < 0.0001) and human epidermal growth factor receptor 2-positive (HER2+) cases (82.5% in HER2+ cancers versus 74.6% in HER2- cancers, P < 0.05)." (PMID 26356670, 2015). "Moreover, EpCAM negative and CD45 negative suspicious elements, with neither endothelial nor macrophagic phenotypes, and morphologically compatible with CTC characteristics were found in both cancer patients and healthy donors." (PMID 26571236, 2015). "The heterogeneity of cancer cells in parental cells containing a mixture of CSC populations has shown a clear indication that the silencing of RARβ might have affected other CSCs populations, but not the CSC that shown positive for CD166+EpCAM+ and CD166-EpCAM-." (PMID 33995625, 2021). "A high proportion of CK positive but EpCAM negative CTCs might be an explanation why Parsortix harvested similar number of CTCs compared to IsoFlux and more than CellSearch, while for spiked PC3 it harvested less cancer cells than IsoFlux and similar number of cancer cells compared to CellSearch." (PMID 26397728, 2015).
adenocarcinoma (78 papers, 2006 to 2026). A common cancer characterized by the presence of malignant glandular cells. "Phase I and II clinical trials have shown that EpCAM IgG mAbs can be safely administered for the treatment of EpCAM-overexpressing adenocarcinomas." (PMID 40358156, 2025). "The comparison with CKpan revealed a generally high concordance with EpCAM staining, especially in adenocarcinomas where both markers were positive in almost 100% of cases." (PMID 38786342, 2024). "The presence of the EPCAM glycoprotein (Figure 1B2), an adenocarcinoma marker, confirmed that these cell clusters primarily consisted of HT29 cells." (PMID 39091906, 2024). "Their comparison resulted in a generally high concordance, especially in adenocarcinomas where both EpCAM and CKpan were positive in almost 100% of cases." (PMID 38786342, 2024). "EpCAM is an epithelial cell marker essential to identify adenocarcinoma whereas CD45 is a lymphocytic marker and can indicate an inflammatory background induced due to urethane." (PMID 35892161, 2022). "It uses an immunomagnetic beads-based approach targeting EpCAM (epithelial cell adhesion molecule) present on the surface of most differentiated CTCs arising from adenocarcinomas." (PMID 35715640, 2022). "Among them, catumaxomab, one of the first FDA-approved trifunctional Abs, binds CD3 on T cells, epithelial cell adhesion molecule (EpCAM) overexpressed on human adenocarcinomas, and the Fc receptors on other immune cells." (PMID 33868786, 2021). "CK7, MUC1 and EpCAM were chosen as representative markers because they are frequently expressed in adenocarcinoma." (PMID 34600546, 2021). "EPCAM protein was expressed in adenocarcinomas of the GI tract, especially in CRC, where it showed a diffuse and strong positivity." (PMID 33003511, 2020). "High-level and mostly homogenous EpCAM expression was found on 85% of adenocarcinomas and on 72% of squamous cell carcinomas." (PMID 30871104, 2019). "Organoids showed global expression of the epithelial marker, EpCAM and the adenocarcinoma marker, CEA CAM1." (PMID 29414601, 2018). "In small-sized adenocarcinomas, Trop2 and EpCAM have opposite biological effects: Trop2 has an unfavorable outcome, while EpCAM has a favorable one." (PMID 26000093, 2015). "Class B cell lines (CLB) are adenocarcinomas exhibiting a pure epithelial morphology and the EpCAM+CD24+CD44+CD133+ phenotype." (PMID 26158412, 2015). "Tumors develop in 100% of the animals in the antrum of the stomach which were first tentatively identified as adenocarcinomas due to the expression of EpCAM and transgenic CEA." (PMID 22253802, 2012). "EpCAM is frequently expressed at high levels on primary tumors and metastases of most human adenocarcinoma." (PMID 20976159, 2010). "Here are some examples: Scirrhous HCC has significantly reduced HepPar1 positivity compared to conventional HCC (26% vs. 74%) while frequently expressing adenocarcinoma-associated markers, including CK7 (53% vs. 2%), CK19 (26% vs. 2%), and epithelial cell adhesion molecule (EpCAM, 63% vs. 11%)." (PMID 40941632, 2025). "In contrast, EpCAM positivity was seen in 100% of 147 adenocarcinomas of the lung." (PMID 38786342, 2024). "The EpCAM+ cells were confirmed as adenocarcinoma using Papanicolaou staining." (PMID 36293034, 2022). "CD326 (the cell surface protein epithelial cell adhesion molecule, EpCAM) was chosen as the targeting moiety because of its high expression level in various adenocarcinoma cell lines and low expression level in normal cells." (PMID 36235009, 2022). "EpCAM (epithelial cell adhesion molecule), is a glycosylated, 30~40 kDa type I transmembrane protein, which was reported to be expressed on essentially all human adenocarcinoma, and is part of the signature of CICs in numerous solid tumors as well as normal stem cells." (PMID 27304054, 2016).
adenocarcinoma (continued). "It is possible that selection for CD49+/EpCAM+ cells in combination with culture conditions to increase ErbB3 expression over EGFR expression may increase the likelihood of generating luminal adenocarcinomas." (PMID 26228788, 2015). "In adenocarcinoma patients, the detection rate was 54.55% (18/33) and 75.75% (25/33) for anti-EpCAM-MNs or a combination of anti-EpCAM-MNs and anti-FRα-MNs, and a significant improvement in enrichment efficiency was obtained with a combination of anti-EpCAM-MNs and anti-FRα-MNs (p = 0.001)." (PMID 29352248, 2018). "Comparative profiling revealed higher EGFR and EPCAM expression in HNSCC versus NSCLC, while MUC1 predominated in NSCLC, particularly in SQCCL; notably, the NSCLC cohort was predominantly adenocarcinoma." (PMID 42203995, 2026). "The CDH1+/EPCAM+ epithelial cells were enriched in adenocarcinoma and adenosquamous tissues but rarely noticed in NET, in which the EPCAM+/INSM1+ neuroendocrine cells were exclusively identified." (PMID 34185421, 2021). "To determine the relative contribution of BM–derived stromal cells, we stained the adenocarcinoma and adjacent lung with antibodies specific for hematopoietic cells (CD45+) and epithelial cells (epithelial cell adhesion molecule, EpCAM+)." (PMID 26046767, 2015). "Based on the expression of the epithelial marker EpCAM in derived tumor cell lines and transgenic human CEA which is widely expressed in mucus-producing epithelial cells and adenocarcinomas we tentatively classified these tumors as adenocarcinomas." (PMID 22253802, 2012). "Then, by staining for squamous epithelium markers (including KRT5, KRT6A, SFN, and KRT14) and columnar epithelium markers (including EPCAM and KRT8), groups 3, 7, and 10 were identified as squamous cancer cells, and groups 5, 6, and 8 were identified as adenocarcinoma cells." (PMID 36052088, 2022). "Of note, though CTCs from patients with neuroendocrine prostate cancer are more frequently nonclassical than those with patients with adenocarcinoma, the RB1 mutation was identified in classical EpCAM+ CTCs." (PMID 28228136, 2017). "Since EpCAM is usually expressed in adenocarcinoma, an excisional biopsy of the right supraclavicular lymph node was performed." (PMID 24137345, 2013). "The present study focused on the differential expression of EpCAM and TROP2 according to SCC or adenocarcinoma (AdC) histology, because certain genetic lesions may play different biological roles depending on the histological subtypes." (PMID 22482828, 2012).
infection (55 papers, 2009 to 2025). The state of being infected such as from the introduction of a foreign agent such as serum, vaccine, antigenic substance or organism. "The infection of human mammary epithelial cells with a high-risk HCMV strain also induced a reduction in the expression of the epithelial cell adhesion molecule (EpCAM)." (PMID 40361452, 2025). "In sum, these data suggest that loss of EpCAM primarily affects epithelial properties of the enveloping cell layer, whereas dysmorphology of the basal layer, hyper-proliferation, apoptosis, infection and inflammation are later or secondary consequences." (PMID 19609345, 2009). "To identify the signaling pathways involved in restricting Shigella replication, we performed bulk RNA sequencing of bead-enriched EpCAM+ epithelial cells isolated from the colon and cecum of mice 48h post-infection." (PMID 40885187, 2025). "We were able to observe VACV infection of resident EpCAM+ γδ T cells, as previously, and a large population of IL-22-producing resident γδ T cells, but production of IL-22 by VACV-infected γδ T cells was minimal." (PMID 38543790, 2024). "PD-L1 expression on the surface of EpCAM+ cells and dead cells with EpCAM+ were increased after OBP-702 infection, similar to the in vitro experiment." (PMID 38745748, 2024). "BALB/c mice infected via nasal route with NY-ESO-1 S-FLU virus displayed a higher level of infection on day 2 in lungs with higher frequency of infected EpCAM+ lung epithelial cells compared to immune cells (identified as CD45+)." (PMID 36626205, 2023). "In vivo, when mice were intranasally (i.n.)infected with 100 PFU of BrightFlu, CD45- EpCAM+ cell infection peaked at day 6 post infection similarly to wildtype PR8." (PMID 37478193, 2023). "Using flow cytometry, we found that the infection-driven IL-33 produced by EpCAM+CD45− cells was significantly reduced in Il17a-KO mice compared to WT controls." (PMID 37783278, 2023). "As predicted by the in vitro data, treatment with gefitinib reduced the phosphorylation of both EGFR and EphA2 in CD45- EpCam+ cells after 1 d of infection." (PMID 33471869, 2021). "Genes for epithelial cell markers such as cytokeratins 14, 18 and 19 (KRT14, KRT18, KRT19), E-cadherin (CDH1) and epithelial cell adhesion molecule (EPCAM) showed the highest expression at 0 hpi and decreased post-infection." (PMID 34740333, 2021). "Remarkably, EVs from EndoC-βH1 cells exhibited strong signals for CD326 (EpCAM) compared with other EV surface markers and its expression was increased by 1.8 fold post-infection." (PMID 33171580, 2020). "In naïve EndoC-βH1 cells infected with EpCAM-positive EVs from E16-infected cells, the results revealed that viral titers increased above background levels within 48 h of infection in a time-dependent manner." (PMID 33171580, 2020). "We infected adenoids with GFP+ WT Mtb or GFP+ Mtb eccD1::Tn and observed more GFP+/EpCAM+/NKM+ cells after infection with WT Mtb as compared to Mtb eccD1::Tn." (PMID 32134383, 2020). "In complementary experiments, we infected mice with our panel of MNV strains and detected MNV genomes and EpCAM transcripts in small intestine sections via RNAscope at 48–72 hours post-infection." (PMID 31329638, 2019). "In Mtb-infected T2DM mice (6 months after infection), the lung epithelial cell lining was severely damaged (disappearance of EpCAM+ cells), and IL-22R1 expression was reduced compared with that of Mtb-infected non-T2DM mice." (PMID 31809521, 2019). "MHC-I expression was determined on EpCAM+ (CD326) lung epithelial cells on day 5 post-infection (p.i.)by flow cytometry." (PMID 26928844, 2016). "The amount of VEGFR2, CCR1, and EpCAM protein in pRNAT-shVCE transfected Huh7 cells also decreased greatly 24, 48, and 72 hours after infection." (PMID 27221035, 2016).